ZEB2 (zinc finger E-box binding homeobox 2)
Diseases named in the same sentence as ZEB2 in open-access papers (continued):
Sharing a sentence is not in itself a finding about the gene and the disease.
infection (24 papers, 2009 to 2025). The state of being infected such as from the introduction of a foreign agent such as serum, vaccine, antigenic substance or organism. "Both in susceptible and young protected groups, ZEB2+ memory CD4+ T cells were significantly expanded during the infection compared to convalescence." (PMID 38001069, 2023). "We found that infection with adenovirus encoding Zeb2 induces increased expression of these myofibroblast markers." (PMID 30336567, 2018). "Over-expression of miR-200b and/or miR-200c in 4TO7 cells, either by transient transfection of miRNA mimics or infection with a miR-141-200c cluster-expressing retrovirus, led to a loss of Zeb2 expression, an increase in E-cadherin expression and the acquisition of an epithelial-like morphology." (PMID 19787069, 2009). "The two largest infection-specific clusters exhibited distinct gene expression patterns, with cluster 0 and cluster 6, enriched in Zeb2 and Gjb6 expression, respectively." (PMID 38767331, 2024). "We observed two infection-specific keratinocyte populations enriched in Zeb2 and Gjb6 expression, respectively, as early as 4 days post-wounding." (PMID 38767331, 2024). "We studied early-activated antiviral effector CD8 T cells 2 weeks after vaccinia inoculation of healthy adults, to assess human ZEB2 upregulation, as is seen in murine models of experimental infection." (PMID 34070208, 2021). "This is indicated by the expression of Zeb2 and Cxcl2 marker genes, which are exclusive to the AM_2 population in uninfected mice, but become up-regulated by AM_2 and IM_1 bystander cells upon infection." (PMID 34292313, 2021). "Levels of ZEB2 were also strongly reduced by infection with the wild type (lanes 2–4) or T67A viruses (lanes 5–7) but not by HSV-1 ΔICP0 (lane 9)." (PMID 28783105, 2017). "Infection with these retroviruses allowed us to produce 4TO7 cell lines that stably expressed the miR141-200c cluster or had stably knocked-down Zeb2." (PMID 19787069, 2009). "Similarly, the T-bet/ZEB2 axis has been shown to promote Teff cell differentiation in response to primary and secondary infection." (PMID 41203628, 2025). "Moreover, CD11c+ atypical B cells, indispensable in limiting recrudescent infection, depend on ZEB2 for recruitment and functioning." (PMID 40510028, 2025). "The immune response in vaccinated or immune individuals is known to be faster and more potent upon infection, likely enabling more rapid containment of microbial pathogens which could involve the ZEB2+ cytolytic memory CD4+ T cells." (PMID 38001069, 2023). "Performing differential gene expression analysis between the aged groups emphasized the presence of the inflationary T-cell phenotype (e.g., expression of Klrg1, Gzma, Zeb2) following infection with MCMV-ie2-gp33 compared to mice infected with acute LCMV or MCMV-m45-gp33." (PMID 36028771, 2022). "Using lineage-restricted Cre lines, ZEB2 has been demonstrated to be essential in regulating T-cell effector and memory cell state changes during infection, controlling macrophage tissue heterogeneity, as well as natural killer (NK) and dendritic cell differentiation and function." (PMID 34550965, 2021). "Tracking the expression of this NF-κB gene signature across infection status reveals a pattern similar to Zeb2 and Cxcl2, suggesting that upon infection with Mtb, a subpopulation of AM_2 cells segregates within the IM_1 cluster, while others mount a pro-inflammatory response that is similar to IM_3." (PMID 34292313, 2021). "This study speculated that HBV may use some unknown strategies, such as DNA methylation, histone acetylation, other transcription factors, or microRNA, to antagonize the attack of ZEB2 and then facilitate its survival in the process of infection." (PMID 26895378, 2016). "We reasoned that an EBV gene expressed early following infection may be responsible for the rapid downregulation of Zeb2 following infection." (PMID 25122803, 2014).
infection (continued). "Intriguingly, when looking at the infected cells, while Zeb2 is expressed by both clusters (AM_2 and IM_1), Cxcl2 is only expressed by IM_1, therefore indicating that subsets of cells in the AM_2 cluster may respond divergently to infection." (PMID 34292313, 2021). "For example, ZEB2 promotes the terminal differentiation of CD8+ effector and memory T-cell populations during infection." (PMID 38674024, 2024). "HRV16 infection also led to a significant increase in expression of genes involved in EMT (e.g., COL1A1, MMP9, SNAI1, and ZEB2) and growth factors (e.g., ~ fourfold for EGF and FGF2, and to a lesser extent TGFB1)." (PMID 34140575, 2021). "Further studies should be conducted to elaborate details of the mechanism of ZEB2-mediated HBV suppression and to assess its role in the actual infection process." (PMID 26895378, 2016). "Murine models have described a role for Zeb2 during the very early stages of the CD8 T cell response to experimental infections, but a similar role in human CD8 differentiation is not known." (PMID 34070208, 2021). "Thus, we measured E‐cadherin levels in MOC1 cells after infection with lentiviruses carrying ZEB1 (MOC1‐ZEB1 cells), ZEB2 (MOC1‐ZEB2 cells), Snail, or a negative control (hereafter referred to as MOC1‐NC cells)." (PMID 39362647, 2024). "Similarly, treatment of HSV-1 infected cells with proteasome inhibitor MG132 added after the onset of the infection was sufficient to stabilize ZEB1, but interestingly not ZEB2, in the presence of HSV-1 expressing either wild type ICP0 or the FXE mutant." (PMID 28783105, 2017).
neurodevelopmental disorder (9 papers, 2019 to 2025). A behavioral and cognitive disorder with onset during the developmental period that involves impaired or aberrant development of intellectual, motor, or social functions. "Additionally, Zeb2 regulates diverse neurodevelopmental processes, and its dysfunction is associated with neurodevelopmental disorders." (PMID 41258036, 2025). "Similarly, ZEB2, a gene linked to neurodevelopmental disorders like Mowat–Wilson syndrome, could contribute to abnormalities in brain formation." (PMID 40843897, 2025). "Three patients harbored four predicted PL/P variants in other genes causing neurodevelopmental disorders (GRIN2B, MADD, TRPM3 and ZEB2), leading to alternative diagnoses for them." (PMID 38566815, 2024). "We now investigated possible functional links between TCF4, MEF2C, ZEB2, UBE3A and ATRX which are all implicated in clinically overlapping, severe human neurodevelopmental disorders." (PMID 31988313, 2020).
genetic disorder (6 papers, 2013 to 2025). "Mowat–Wilson syndrome is a rare genetic disease due to a heterozygous deletion or function loss of the ZEB2 gene located on chromosome 2." (PMID 38397281, 2024). "Mowat–Wilson syndrome (MWS) is a rare genetic disease resulting from heterozygous mutations in ZEB2 causing disease by haploinsufficiency." (PMID 34070208, 2021). "Heterozygous mutations in ZEB2 underlie Mowat–Wilson syndrome (MWS; OMIM #235730), a rare genetic disorder first described in 1998, with more than 300 patients reported to date." (PMID 34070208, 2021).
kidney diseases (5 papers, 2019 to 2025). "Our findings highlight the m6A-mediated regulation of RF through ZEB2, revealing a novel therapeutic target for RF treatment and enhancing our understanding of the impact of mRNA methylation on kidney disease." (PMID 39059495, 2024). "This study suggested that m6A triggers the progression of RF via ZEB2, which provides a new therapeutic target for RF treatment while expanding our understanding of the role of mRNA methylation in kidney disease." (PMID 39059495, 2024). "ZEB2 is also involved in the development of some forms of kidney diseases." (PMID 32149094, 2020).
adenocarcinoma (4 papers, 2017 to 2023). A common cancer characterized by the presence of malignant glandular cells. "In primary adenocarcinoma of the colon, IL-6R expression has been positively correlated with EMT-associated mesenchymal markers SNAIL, SLUG, VIM, ZEB1, and ZEB2." (PMID 31741710, 2019). "In fact, we found that patients with adenocarcinoma harboring somatic mutations of EGFR, CTLA4, PDCD1LG2, or ZEB2 that only underwent surgical treatment and developed brain metastases may have the worst prognosis." (PMID 36629526, 2023). "Single cell gene analysis showed that some SCCs positive for KRT14 expressed the adenocarcinoma marker KRT8 as well as the EMT markers VIM, and ZEB2." (PMID 29079795, 2017).
bacterial infections (1 paper, 2023). "The transcription factor (TF) ZEB2 was shown to drive the onset of terminally differentiated KLRG1hi effector CD8+ T cells in murine models of viral and bacterial infections, likely under the transcriptional control of T-BET63,64." (PMID 38001069, 2023).
cardiovascular diseases (1 paper, 2024). "Previous data have shown that zinc finger E-box binding homeobox 2 (ZEB2) is closely related to the development of cardiovascular diseases." (PMID 38566808, 2024).
ischaemic heart disease (1 paper, 2024). "Here, we report that transcription factor zinc finger E-box-binding homeobox 2 (ZEB2) is induced by hypoxia-inducible factor 1-alpha (HIF1α) in hypoxic cardiomyocytes and regulates a network of genes involved in Ca2+ handling and contractility during ischaemic heart disease." (PMID 39308239, 2024).
psychiatric disorder (1 paper, 2020). A disorder characterized by behavioral and/or psychological abnormalities, often accompanied by physical symptoms. "Among them SPATS2L, ZEB2, KCHN8, and MRPL13 which have been previously connected to psychiatric disorders with the latter two being responsive to nicotine treatment." (PMID 33004014, 2020).
ZEB2 also shares sentences with these, for which no sentence is quoted: developmental delay (5 papers); breast invasive carcinoma (4); lymph node (4); colon adenocarcinoma (3); Angelman syndrome (2); chordoma (2); cognitive deficits (2); Ehlers-Danlos syndrome (2); heart failure (2); intrahepatic cholangiocarcinoma (2); Kabuki syndrome (2); laryngeal squamous cell carcinoma (2); liver cirrhosis (2); myopia (2); nervous system disorder (2); acute liver failure (1); acute myocardial infarction (1); alcoholic liver diseases (1); Anisometropia (1); aortic valve stenosis (1); Ataxia (1); bipolar disorder (1); bladder tumors (1); brain glioma (1); Cantu syndrome (1); cardiofaciocutaneous syndrome (1); cardiomyopathy (1); cataract (1); Char syndrome (1); chlamydial infection (1).
A further 82 diseases each share a sentence with ZEB2 in 1 paper.